CLEC10A (C-type lectin domain containing 10A)
Diseases named in the same sentence as CLEC10A in open-access papers (continued):
Sharing a sentence is not in itself a finding about the gene and the disease.
cancer (63 papers, 2010 to 2026). A tumor composed of atypical neoplastic, often pleomorphic cells that invade other tissues. "Tn/STn antigens are cancer-associated glycans recognized by the human macrophage galactose binding glycoreceptor MGL (CLEC10A/CD301) that is expressed on immature and tolerogenic dendritic cells and macrophages." (PMID 26021314, 2015). "Currently, CLEC10A is being investigated as a cancer immunotherapy target due to its ability to modulate innate and adaptive immunity." (PMID 37507593, 2023). "From six LUAD studies of GEO and TCGA database, CLEC10A expressed lowly in LUAD compared to non‐cancer tissues." (PMID 33655701, 2021). "The role of CLEC10A in enhancing the anticancer effects of immune cells has undoubtedly drawn the interest of researchers, and it has been identified as a potential target for cancer immunotherapy treatment." (PMID 35281077, 2022). "CLEC10A, (C‐type lectin domain family 10, member A), as the member of C‐type lectin receptors (CLRs), plays a vital role in modulating innate immunity and adaptive immunity and has shown great potential as an immunotherapy target for cancers." (PMID 33655701, 2021). "Cancer-associated aberrant glycosylation, especially the Tn and STn antigens, can be detected using the macrophage galactose-type C-type lectin (MGL/CLEC10A/CD301), which has been shown to be a promising tool for CRC prognosis." (PMID 32752259, 2020). "We asked whether the collective evidence of the role of ligands of CLEC10A, such as promoting DC maturation, T cell activation, and initiation of an immune response would coalesce into an effective anti-cancer therapy." (PMID 29665849, 2018). "The identified membrane proteins serve as receptors (EPHB6, ACKR1, and EDNRB) or adhesion molecules (EPCAM) and may enhance antitumor immunity (TENM2 and CLEC‐10A); thus, they may contribute to enhanced mEHT‐induced cancer destruction through regulating the TME related immune response." (PMID 38217262, 2024). "Analysis of transcriptome from more than 1,200 clinical samples including four geographic regions indicated that CLEC10A mRNA levels lower obviously in LUAD than in non‐cancer lung tissue, whether viewed from the overall sample or from the matched sample of a single patient." (PMID 33655701, 2021). "In regard to these results, some of the members of the C-type lectin superfamily like CLEC19A consist of CLEC10A, CLEC2, and CLEC9A suppressed cell proliferation, migration, and invasion, and also cell cycle arrest, and promoted apoptosis in cancer cells." (PMID 38167030, 2024). "Of these, S100A8, CLEC10A, and TFDP2 exhibited significantly different expression profiles between cancer and precancerous stages." (PMID 34745098, 2021). "When we separately analyzed TNBC and ER+ / HER2+ cancer cells, we found no major differences in levels of CLEC10A expression, but significant differences in the number of CLEC10A expressing cells." (PMID 38206856, 2024). "The CLEC10A expression in most cancers was significantly lower compared with non-tumoral tissue, and the decreased expression was related to poor prognosis." (PMID 35887121, 2022). "CD301 (CLEC10A, C-type lectin domain family 10, member A) has not been reported in cancer either, but like any adhesion receptor it has the potential to mediate metastasis." (PMID 23251904, 2012).
infection (20 papers, 2013 to 2025). The state of being infected such as from the introduction of a foreign agent such as serum, vaccine, antigenic substance or organism. "Among others, C-type lectins, such as CLEC10A, a macrophage glycoreceptor for the uptake of pathogens and damaged cells, were upregulated upon infection." (PMID 37790937, 2023). "We then proceeded to demonstrate that knockdown of MGL (CLEC10A) reduced infections by 47–88%." (PMID 23573288, 2013). "Although the sheep MGL proteins have not yet been characterized, sheep do possess a CLEC10A gene that has been shown to be up-regulated in liver tissue of infected sheep at 8 weeks post-infection compared to the control group." (PMID 41008542, 2025).
CLEC10A also shares sentences with these, for which no sentence is quoted: prostate carcinoma (12 papers); germ cell tumor (11); HIV-1 infection (9); autoimmune disease (8); amyotrophic lateral sclerosis (6); lymphoma (6); schizophrenia (6); glioma (4); hepatocellular carcinoma (4); leukemia (4); multiple sclerosis (4); systemic lupus erythematosus (4); colorectal cancer (3); lymph node metastases (3); neurodegenerative disease (3); pancreatic cancer (3); teratocarcinoma (3); triple-negative breast carcinoma (3); Alzheimer disease (2); autoimmune disorders (2); bipolar disorder (2); hepatoblastoma (2); liver cirrhosis (2); lung carcinoma (2); malignant glioma (2); neurological disease (2); psoriasis (2); rhabdoid tumor (2); rheumatoid arthritis (2); seminoma (2).
A further 47 diseases each share a sentence with CLEC10A in 2 papers or fewer.